IL6 (interleukin 6)
Diseases named in the same sentence as IL6 in open-access papers (continued):
Sharing a sentence is not in itself a finding about the gene and the disease.
tumor (continued). "M2 macrophages secrete anti-inflammatory cytokines, such as IL-6, IL-10, IL-13, TGF-β, and chemokines and proteases, such as Arginase1, MMP, and VEGF-A, which promote tumor growth, angiogenesis, and metastasis." (PMID 35895109, 2023). "Based on published data demonstrating that the IL-6/STAT3 axis accelerates EMT and leads to further tumor progression." (PMID 36814597, 2023). "On ELISA of tumor lysates of core and edge samples, edge lysates demonstrated statistically significant elevations in cytokines TNF-α, IL-1β and IL-6 compared to core lysates." (PMID 37752585, 2023). "Conversely, the expression levels of IL6 and CHRNA5 were lower in tumor-free patients after initial treatment compared to those who still had remaining tumors." (PMID 37509183, 2023). "Our previous studies showed a high expression of IL-6/STAT3 pathway proteins in human PDAC specimens and promising results for tumor growth inhibition by blocking this signaling." (PMID 36495330, 2023). "The inflammatory processes in the breast are viewed as a favorable environment for tumor cell metastasis, and VEGF expression facilitated by IL-6 exacerbates this." (PMID 36873124, 2023). "PepO-primed M2 macrophages decreased the expression of tumor-supportive molecules like Arg-1, Tgfb, Vegfa and IL-10, and increased the expression of iNOS, Cxcl9, Cxcl10, TNF-α and IL-6 to inhibit TNBC growth." (PMID 37925462, 2023). "In TAMs, proinflammatory cytokines such as IL-6, which are overproduced in the TME due to their release by tumor cells, together with some defensive cells, play a crucial role in tumor growth and metastasis." (PMID 36768935, 2023). "In turn, HSC-derived IL6 was able to promote HCC progression in mice through the induction of myeloid-derived suppressor cells (MDSCs), thereby modulating the tumor environment." (PMID 37620309, 2023). "Another potential target is pro-inflammatory cytokines and chemokines, such as IL-6, IL-8, IL-1β, and TNF-α, which contribute to the promotion of tumor growth, angiogenesis, and metastasis." (PMID 37760801, 2023). "We have yet to determine if these early responses are IL-6-dependent, as our 4T1-IL6-KO studies focused on late-stage tumor development." (PMID 36142210, 2022). "Meanwhile, we also identified the impacts of IL-6 on proliferation capacity in OSCC cells and xenograft tumor of model mice." (PMID 35513871, 2022). "After blocking IL-6/JAK2/STAT3 pathway and inhibiting DNMT1, the proliferation of lung CSCs, the formation of spheres and the ability to initiate tumor growth decrease." (PMID 36591515, 2022). "Our results suggest iCAFs as the main cell type expressing IL6, CXCL12, and LIF in the tumor milieu, wherein these ligands promote immunosuppressive changes, such as macrophage polarization, toward the M2 phenotype." (PMID 35196078, 2022). "The arrival of IL-6 also enhances breast CSC migration, promotes tumor growth and metastasis, and induces angiogenesis by inducing the expression of proangiogenic molecules, such as VEGF, MMP2 and MMP9." (PMID 36497411, 2022). "We further tested the levels of cytokines in the serum of tumor-bearing mice and found that FAVO increased the serum levels of IL-2 and IFN-γ but reduced the serum level of IL-6." (PMID 35392643, 2022). "Macrophages express IL-6, TNF-alpha, and cathepsin B to activate STAT3 pathways in tumor cells, which increases the proliferation and survival of cancer cells treated with various chemotherapeutics." (PMID 35183252, 2022). "IL-6/JAK2/STAT3 pathway has considerable potential in inhibiting tumor growth and restoring anti-tumor immunity." (PMID 36591515, 2022). "IL-6 activates downstream molecules such as STAT3 by binding to its receptor, which allows tumor cells to survive in a highly toxic inflammatory environment." (PMID 36698392, 2022). "Here, we showed that CBX7 blocked tumor proliferation through inactivation of the TNF pathway and regulated sensitivity to TKIs via the TNFα/IL6 axis." (PMID 35342353, 2022).
tumor (continued). "The researchers demonstrated that co-cultures of melanoma and prostate cancer multicellular tumor spheres (MCTS) produced little M-CSF and IL-6, but high lactate levels." (PMID 35444235, 2022). "Several paracrine factors, such as VEGF growth factor, IL6, and IL10 cytokines, are produced in cells undergoing lytic replication to modulate the tumor microenvironment to support the growth of the tumor cells." (PMID 36560704, 2022). "IL-6 stimulates the invasion and growth of GBM tumor cells by binding to heterogeneous membrane receptor complexes (formed by IL-6r and glycoprotein 130) and initiating typical IL-6 signal transduction, such as STAT3." (PMID 35572545, 2022). "The IL6-JAK-STAT3 pathway promotes the proliferation, survival, invasiveness, and metastasis of tumor cells; induces the production of pro-angiogenic factors; and has a significant influence on TIICs." (PMID 36614001, 2022). "The activated mast cells also produce IL1β, IL6, IL8, IL13, TGFβ, TNFα, PDGF, and VEGF for promoting tumor growth and metastasis directly, and also indirectly by provoking angiogenesis and immune chaos." (PMID 36211375, 2022). "Indeed, in the same study, tumour suppression was abolished upon treatment with anti-IL-6 monoclonal antibodies; the inhibition of immune effector responses, which in part is co-ordinated by IL-6, may explain this finding." (PMID 35359426, 2022). "IL-6 also promotes MDSC accumulation and inhibits anti-tumor immunity by activating the JAK/STAT3 signaling pathway, which results in increased production of ROS, NO, and PD-L1." (PMID 36246629, 2022). "This is associated with the production of immunosuppressive cytokines, such as IL-6, IL-10, and downregulation of MHC I by cancer cells, which reduces the maturation of dendritic cell (DC) and lower Treg recruitment into the tumor microenvironment (TME)." (PMID 36430176, 2022). "LIF along with its receptor (LIFR) form a part of the interleukin-6 (IL-6) cytokine family LIF/LIFR signaling pathway, which plays an important role in tumor progression, stemness, and resistance to therapy." (PMID 36567312, 2022). "M1 macrophages can be induced by IFN-γ and lipopolysaccharide (LPS) and can directly attack tumor cells or pathogens and promote inflammatory effects by releasing cytokines like TNF-α, IL-6, IL-12, IL-18." (PMID 35646915, 2022). "Mice with 4T1 tumours also had a subtler increase in CXCL13 relative to normal levels, and a subtle increase in IL-6 and a subtle decrease in CXCL1 compared to CT26-bearing animals." (PMID 35226704, 2022). "IL6 and IL10 were known to be key pro-tumor cytokines that exerts multiple functions in the development of liver tumors, including promoting proliferation, EMT, angiogenesis, anti-apoptosis, and immune surveillance evasion." (PMID 36238304, 2022). "When the cGAS-STING pathway in tumor cells is activated, cytokines such as IL-6 and type I IFN are induced, leading to tumor cell apoptosis or death." (PMID 35889509, 2022). "By using CRISPR to knock out IL-6 in the 4T1 cell line (4T1-IL6-KO), a unique opportunity was provided to evaluate the effect of excess IL-6 originating specifically from the tumor cells." (PMID 36142210, 2022). "We found that the high-risk group was significantly associated with higher expression level of immune checkpoints and immune inhibitory factors, including CCL2, CTLA4, CXCR4, IL6, LAG3, PDCD1, and TGFB1, indicating tumor immune evasion." (PMID 36092894, 2022). "Tumor cells induce various inflammatory cytokines, including TNF-α, IL-1β, IL-6, IL-17/18, and IL-23, and growth factors (G-CSF, GM-CSF, and IL-3) to generate neutrophil production and confirm their survival." (PMID 36091114, 2022).
tumor (continued). "M1 macrophages promote beneficial anti-tumor effects by driving the Th1 response and via the secretion of TNF-α, IL-1, IL-6, IL-12, Type I IFN, CXCL1-3, CXCL5, and CXCL8-10." (PMID 35345849, 2022). "By secreting multiple cytokines and chemokines, CAFs facilitate immune escape (e.g., IL-6, IL-1, and FGF), recruit immunosuppressive cell infiltration, and suppress the ability of cytotoxic lymphocytes to kill tumor cells." (PMID 35953863, 2022). "For instance, inflammatory cytokines such as IL-1β, IL-6, IL-17, IL-18, IL-23, and TNF-α can lead to tumor growth through activation of pathways such as NF-κB and STAT351–54." (PMID 36085201, 2022). "In contrast, TLR4, NOS2, IL-6, MIP-3α, and VEGF were highly expressed in the transplanted tumour tissues from the LPS groups, and their expression levels were decreased in the TLR4-silenced groups." (PMID 36010574, 2022). "IL-6 stimulates hyperactivation of JAK/STAT3 signaling, which promotes tumor proliferation, angiogenesis, invasiveness, and immunosuppression." (PMID 35136076, 2022). "Both IL-10 and IL-6 induce activation of STAT3, but IL-6 induces proliferation and the production of inflammatory cytokines that promote tumor growth and is also considered to be a strong driver of many chronic inflammatory diseases." (PMID 35433880, 2022). "Ovarian mesenchymal stem cells (OvMSCs) secrete IL-6 and SKOV3 cells exposed to this conditioned media, resulting in enhanced tumor sphere formation and activation of STAT3." (PMID 36550571, 2022). "The ability of IL-6/STAT3 to modulate additional tumor-promoting and tumor-suppressing pathways have been extensively investigated." (PMID 35406728, 2022). "Zinc enriches the microbiome in Prevotella, Proteobacteria and Actinobacteria and improves the function of the immune system by increasing the level of pro-inflammatory cytokines such as IL-1β, IL-2, IL-6, TNF-α and IFN-γ in the tumor environment." (PMID 36428677, 2022). "In BlCa, IL-6, CCL2, CXCL1, CXCL12, IL-8 and TGF-β1 play putative roles in promoting tumor progression, growth, invasion, and metastases formation." (PMID 36699696, 2022). "Notch1 contributes to an immune-suppressive tumor microenvironment by inhibiting the expression of SNAP23 and overexpression of IL-6, IL-8, and CCL5 downstream of the pathway, thus affecting the efficacy of immune-checkpoint inhibitors." (PMID 36119081, 2022). "CK2 inhibitors can reduce the release of TNF, IL-6, and VEGF cytokine in cancer cells.CK2 inhibitors can suppress the production of tumor-derived factors (TDF) to modulate immune cells development and promote tumor regression." (PMID 36530985, 2022). "Modulation, microglial inflammation, and bidirectional inhiation, along with primary pro-inflammatory cytokines possessing interleukin 6 (IL-6), resulting in a transformation growth factor (TGF-β1), as well as a TNF-α, is defined as tumor necrosis." (PMID 36291661, 2022). "Upon tumor engagement, CAR T-cell secrete pro-inflammatory cytokines such as GM-CSF and IL-8, which promote the release of the major CRS biomarker IL-6 as well as IL-8, cytokines that were previously shown to be monocyte-dependent." (PMID 36405594, 2022). "On the other hand, tumor IL-6 levels were similar for control and the LDL-TO groups, while the LDL-DHA treatment resulted in a precipitous drop in IL-6." (PMID 36505796, 2022). "The tumour suppressor microRNA-122 (miR-122) is thought to decrease the expression of VEGF, IL-6, COX-2, prostaglandin E2 and MMP-9." (PMID 35572649, 2022). "Mast cells release matrix metalloproteinases (MMPs) that aid tumor invasion and they actively stimulate neovascularization by producing conventional proangiogenic factors like VEGF, PDGF, and IL-6." (PMID 36532719, 2022). "Based on the dynamic results for these four cytokines, like TNF-α, IL-2, IL-6 and IFN-γ were secreted at higher levels in the high tumor burden group than in the low tumor burden group, but the differences were not obvious." (PMID 35013456, 2022).
tumor (continued). "ICT effectively reduces the tumor weight and volume and prolongs survival in an HCC cell-bearing in vivo SCID model by inhibiting SphK1 and IL-6/JAK/STAT3." (PMID 35600861, 2022). "For instance, TAM produces anti-inflammatory and growth-promoting cytokines, such as IL-10, IL-6, TGF-β, and prostaglandin E2 (PGE2), to restrict cytotoxic function of T lymphocytes and promote tumor growth." (PMID 36679900, 2022). "The amounts of IL-6 and TNF-α in tumor supernatants were 3.5-7.5 times and 5-6 times higher, respectively, compared to the corresponding levels of these cytokines in the blood." (PMID 36330464, 2022). "These transcription factors result in the secretion of pro-inflammatory cytokines that also promote tumor growth, such as TNF-a, IL-1β, and IL-6." (PMID 35053599, 2022). "An example of the “conversation” between tumour cells and CAFs comes from pancreatic ductal adenocarcinoma (PDAC), IL-6 derived from CAFs was modulated by retinoic acid, which was in turn associated with the EMT process of the tumour cells." (PMID 36555218, 2022). "Simultaneous infection of stromal and tumor cells; Upregulation of Fez1 and Pycard; Downregulation of DLL-4, Angiopoietin 2, PECAM, Tie-1, and FOS EGR2, CREB-5, IL-6, Map2K1, CCL22, TIMD4 and CCL19." (PMID 35640930, 2022). "First of all, M2 TAMs secrete cytokines such as IL-6 and CXCL-8 into the TME and directly promotes the growth of tumor cells." (PMID 35145526, 2022). "In spleen cell supernatants, IFN-γ, IL-4, IL-1β, IL-6, IL-13, MCP-1, and IL-21 were significantly higher in the tumour-bearing SID animals compared to the healthy controls." (PMID 36010845, 2022). "TAMs secret IL-6, and IL-6/signal transducer and activator of transcription 3 (STAT3) signaling pathway mediates the resistance in tumor to chemotherapy drugs." (PMID 35193986, 2022). "This leads us to deduce that FAT1 probably employs both cell growth-promoting features of some cytokines (such as IL-6) and immunity-evading properties of others (such as TGF-β) to the advantage of the tumor." (PMID 35720420, 2022). "IL-6 is then involved in signaling and transcription of activator 3 (STAT3) in immune cells, stromal cells, and tumor cells to complete immune escape and realize cancer cell metastasis." (PMID 36741380, 2022). "They involve STAT3-inducing cytokines (IL-10, IL-6 and LIF), TGFB1 mainly expressed by TAMs, WNT7A mainly expressed by tumor cells, multiple S100 genes, semaphorins and their receptors (plexins and neuropilins), ephrins, chemokines and their receptors." (PMID 35682890, 2022). "In particular, propolis promotes the release of TNF-α, IL-6, IL-12, MHC molecules, and IFNs, which are crucial for the activation of NK cells and cytotoxic T lymphocytes and induction of tumor cell death via apoptosis, autophagy, and programmed necrosis." (PMID 36142391, 2022). "In turn, EVs secreted by MMA-induced CAFs, harboring IL-6 and other factors, promote an EMT in tumor cells, fostering the acquisition of aggressive traits including drug resistance and increased metastatic formation." (PMID 36266345, 2022). "Cancer-associated adipocytes (CAA) are important players of the TME being involved in tumor progression, angiogenesis, invasion, metastasis, and drug resistance through the secretion of adipokines such as leptin, adiponectin, CCL2, CCL5 and IL6." (PMID 36114508, 2022). "Tumor cells recruit and secrete growth factors such as transforming growth factor β (TGFβ), platelet-derived growth factor (PDGF), and interleukin-6 (IL-6) to stimulate fibroblasts to convert to CAFs." (PMID 36505831, 2022). "In vitro, IL6/LIF increased tumor cell estrogen receptor expression and signaling, and combination cytokine blockade and AET resulted in synergistic inhibition of tumor cell growth." (PMID 36230597, 2022). "IL-6 is a well-established tumor-promoting cytokine among the IL-6 family of cytokines, which activates multiple STAT3-mediated tumor initiation and progression pathways." (PMID 36010693, 2022).
tumor (continued). "Elevated levels of CAF-derived IL-6 induces the activation of the JAK/STAT3 signaling pathway, leading to tumor cell proliferation mediated by the activation of cyclin D1, among other cell cycle mediators." (PMID 36010899, 2022). "This led to an upsurge in microglial production of IL-6 and subsequently MMP2, which accelerated tumor migration, invasion, and gliomagenesis." (PMID 35419058, 2022). "Exosomal miR-106b found in colorectal cancer also suppresses PDCD4 driving both IL-6/STAT3 and mTOR signalling to promoting regulatory polarization in tumor macrophages." (PMID 35320943, 2022). "In vivo, stromal deletion of PKN2 also resulted in a shift from myCAF to iCAF signatures in orthotopic murine tumours, accompanied by enhanced EMT and IL6‐JAK‐STAT3 signalling." (PMID 35533046, 2022). "IL-6 is abundantly present in the TME, and an abnormally activated IL-6/STAT3 signaling pathway can play a role in the occurrence and development of HCC by affecting tumor cell proliferation, migration, invasion, angiogenesis, and apoptosis." (PMID 35757756, 2022). "Neutrophils and macrophages secrete tumour-growth-promoting factors, including VEGF, HGF, IL-6, IL-8, MMPs, and elastases." (PMID 36077723, 2022). "Typically, cytokines mattering immune activation and CAR‐T replication (IL‐2, IL‐6, TNF‐α, and IFN‐γ) are drastically increased, hinting at the replication and function maintenance of CAR‐T cells for executing anti‐tumor actions." (PMID 36156442, 2022). "The IL-6/JAK2/STAT3 pathway and CXCL12/CXCR4 interactions between tumor cells and CAFs were enriched." (PMID 35784460, 2022). "0.5 × 106 Panc47 FAK-wt, FAK−/−, FAK-wt CTL shRNA, FAK-wt IL6 shRNA1, or FAK-wt shRNA2 cells were implanted into the pancreas of C57BL/6 mice, mice sacrificed 2 weeks post-implantation and tumours weighed." (PMID 36138073, 2022). "In both CRC subtypes, the pro-inflammatory cytokines IL1-β, IL-6 and TNF upregulate the chemokines CXCL-1/2/3/5/6/8 in CAFs, monocytes and cancer cells; this attracts CXCR1/2-positive neutrophils to the tumor." (PMID 36611932, 2022). "Considering the important role of TIME in immunotherapy, we explored the correlation between IL-6 expression and the TIME in tumor samples with NSCLC from the CICAMS cohort." (PMID 35550592, 2022). "High levels of PTHrP, IL-6, and RANKL have been detected in both OS samples and cell lines, suggesting local production of cytokines and growth factors as a mechanism for tumor cells to enhance osteoclastogenesis." (PMID 35646939, 2022). "Interleukin 6 (IL-6) is released by macrophages, T cells, and fibroblasts in the TME and maintains a pro-tumor environment on other cells in the TME to encourage tumor evasion and angiogenesis." (PMID 36550571, 2022). "Stimulated the secretion of IL-6, IL-1β, and IFN-β;Enhanced infiltration of leukocytes and dramatic tumor growth inhibition." (PMID 35748543, 2022). "In a loop of cytokine signalling, IL-6 from SCs through the STAT3 pathway triggered tumour cell EMT and migration, while tumour-derived IL-1β activated the NF-kappa B pathway in glia and further induced SC cytokine secretion from SCs." (PMID 35269454, 2022). "As one mechanism of LIPG in the regulation of tumor cell oxidative metabolism, LIPG mediates histone deacetylase 6 (HDAC6) and histone acetylation, which contribute to changes in IL-6 and fatty acid synthesis gene expression." (PMID 35954428, 2022). "We further studied the expression of suppressive function-related genes in MDSCs, and the IL-10, IL-6, and TGF-β signaling pathways were upregulated after cryo-thermal therapy compared with those in tumor-bearing control." (PMID 36389684, 2022). "Finally, KPC tumor cells demonstrated significantly higher pSTAT3 expression when incubated with conditioned media (CM) from intratumoral neutrophil-CAF co-cultures alone compared with CM from neutrophil-CAF co-cultures treated with either anti-IL-1β or anti-IL-6 neutralizing antibodies." (PMID 36107485, 2022).